NLRP3 (NLR family pyrin domain containing 3)
Diseases named in the same sentence as NLRP3 in open-access papers (continued):
Sharing a sentence is not in itself a finding about the gene and the disease.
cryopyrin-associated periodic syndrome (continued). "NLRP3 mutations have been implicated in hereditary inflammatory diseases and are grouped under cryopyrin-associated periodic syndromes (CAPS) or cryopyrinopathies." (PMID 22529966, 2012). "Furthermore, hereditary mutations in NLRP3 rendering the protein constitutively active, are directly linked to cryopyrin-associated periodic syndromes (CAPS)." (PMID 20482797, 2010). "Cryopyrin-associated periodic syndromes (CAPS) are a group of rare hereditary autoinflammatory diseases caused by an overproduction and excessive activation of interleukin-1β, which, in turn, results from gain-of-function mutations in the NLRP3 gene." (PMID 40539069, 2025). "Mutations in the NLRP3 gene are responsible for Muckle–Wells syndrome (MWS), chronic infantile neurologic cutaneous syndrome (CINCA), and cryopyrin-associated periodic syndromes (CAPS), which present with fevers, aseptic meningitis, arthritis, and cutaneous inflammation of variable severity." (PMID 39791736, 2025). "Furthermore, gain-of-function mutations occurring within or in the close vicinity of the central NACHT domain of NLRP3 give rise to three autosomal dominantly inherited periodic fever syndromes collectively referred to as cryopyrin-associated periodic syndrome (CAPS)." (PMID 38519142, 2024). "A well-established causal relationship between gain of function mutations of NLRP3, resulting in excessive inflammasome activation with subsequent overproduction of IL-1β, and disease can be found for autoinflammatory conditions called cryopyrin-associated periodic syndromes (CAPS)." (PMID 35800898, 2022). "Surprisingly, patients with Cryopyrin-associated periodic syndrome (CAPS), which is caused by a gain-of-function mutations in the NLRP3 gene, do develop recurrent fever, uveitis and arthritis, similar to XIAP deficient patients, but do not develop HLH, splenomegaly or IBD." (PMID 34222142, 2021). "In the chronic diseases driven by inflammation, such as type 2 diabetes and cryopyrin-associated periodic syndromes (CAPS), the NLRP3 inflammasome is dysregulated, resulting in the uncontrolled release of pro-inflammatory cytokine IL-1β, which drives inflammation in such diseases." (PMID 34439904, 2021). "Cryopyrin-associated periodic syndrome (CAPS) is a life-long, autoinflammatory disease associated with a gain-of-function mutation in the nucleotide-binding domain, leucine-rich repeat family, pyrin domain containing 3 (NLRP3) gene, which codes for cryopyrin." (PMID 34059097, 2021). "MCC950 interacts with the NACHT domain of wild type NLRP3 but not with NLRP3 mutants associated with cryopyrin-associated periodic syndrome (CAPS), suggesting that there is a lack of effectiveness in that type of pathologies." (PMID 34829842, 2021). "Cryopyrin-associated periodic syndrome (CAPS) is a rare autoinflammatory syndrome characterized by overproduction of interleukin (IL)-1β, resulting from dysregulated NOD-like receptor family pyrin domain containing 3 (NLRP3) inflammasome activity." (PMID 34099791, 2021). "These hereditary cryopyrin-associated periodic syndromes (CAPS) are typified by chronic inflammatory symptomology caused by point mutations in the NLR family gene NLRP3, resulting in the production of a hyperactive NLRP3 protein." (PMID 32680528, 2020). "However, its clinical indications were extended, in 2003, to other conditions such as cryopyrin-associated periodic syndrome (CAPS), a group of rare inherited autoinflammatory diseases generally caused by autosomal-dominant mutations in the NLRP3 gene." (PMID 32751171, 2020). "A more recent paper on the rare disease cryopyrin-associated periodic syndromes (CAPS, caused by NLRP3 mutations and consequent overproduction of IL-1β) suggested that MDSCs might act in an anti-inflammatory manner and exert beneficial effects." (PMID 31156644, 2019).
cryopyrin-associated periodic syndrome (continued). "Thus, NLRP3 mutations lead to cryopyrin-associated periodic syndromes (CAPS), such as familial cold autoinflammatory syndrome, Muckle–Wells Syndrome and neonatal onset multi-systemic inflammatory disease/chronic infantile neurological cutaneous articular syndrome." (PMID 31547225, 2019). "Heterozygous mutations in the NLRP3 gene observed in patients with cryopyrin associated periodic syndrome (CAPS) lead to a hyper-responsive inflammasome that does not require a second signal for activation." (PMID 29322034, 2017). "Patients suffering from Cryopyrin-associated periodic syndrome (CAPS), due to GOF mutations in the inflammasome receptor NLRP3, present with severe cutaneous rashes." (PMID 38649745, 2024). "NLRP3-associated autoinflammatory disease (NLRP3-AID), often referred to as cryopyrin-associated periodic syndrome (CAPS), is a rare, heterogeneous disease entity caused by variants in the NLR family pyrin domain containing-3 (NLRP3) gene on chromosome 1q44." (PMID 37480029, 2023). "NLRP3-associated autoinflammatory disease (NLRP3-AID) is one of the first recognized autoinflammatory diseases, also recognized as Cryopyrin-associated periodic syndromes (CAPS) before." (PMID 35668534, 2022). "Gain-of-function mutations of NLRP3 and NLRC4 have been associated with autoimmune diseases which overlap in their symptoms, termed cryopyrin-associated periodic syndromes (CAPS)." (PMID 30042333, 2018). "However, its clinical indications have been extended so far to other diseases such as the cryopyrin-associated periodic syndromes (CAPS), a group of rare inherited auto-inflammatory diseases associated to pathogenic variants in the IL-1-regulating genes NLRP3 and ILRN." (PMID 28659798, 2017). "This includes two of the NLRP3 SNPs, R260W and D303N (NOD2 R334 and D382), which are associated with cryopyrin-associated periodic syndromes (CAPS) gain of function diseases Muckle–Wells syndrome and Neonatal Onset Multisystem Inflammatory Disease." (PMID 25093298, 2014). "Two oral NLRP3 inhibitors produced by Inflazome, inzomelid (clinical trials identifier: NCT04086602) and Somalix, are intended for the treatment of cryopyrin-associated periodic syndrome (CAPS) and cardiovascular disease, respectively." (PMID 38256186, 2024). "TNRSF1A, NLRP3 and MVK gene mutations are associated with three other hereditary recurrent fevers, namely TNF-α receptor-associated periodic syndrome (TRAPS), cryopyrin-associated periodic syndromes (CAPS) and mevalonate kinase deficiency." (PMID 37504266, 2023). "The pharmaceutical company Inflazome (Roche) has developed two oral NLRP3 inhibitors, Inzomelid (NCT04086602) and Somalix, both of which have completed Phase 1 trials and have been tested in people with Cryopyrin-associated periodic syndrome (CAPS)." (PMID 35755447, 2022). "Aligning with a key role for the NLRP3 inflammasome in sustaining the human Th1 response, CD4+ T cells from patients that suffer from cryopyrin-associated periodic syndromes (CAPS) due to gain-of-function mutations in NLRP3, display also significantly increased IFN-γ production." (PMID 30305631, 2018). "The best known HRF are Familiar Mediterranean Fever (FMF), Cryopyrin-Associated Periodic Syndrome (CAPS), TNF-receptor associated periodic fever syndrome (TRAPS) and Mevalonate-Kinase Deficiency (MKD), caused by mutations in MEFV, NLRP3, TNFRSF1A and MVK genes, respectively." (PMID 29047407, 2017). "Cryopyrin-associated periodic syndrome (CAPS) includes a spectrum of apparently distinct inflammatory disorders of increasing severity: FCAS, MWS, and CINCAs, all caused by NLRP3 mutations, though the molecular basis for this distinction is still not well-understood." (PMID 25132737, 2014).
cryopyrin-associated periodic syndrome (continued). "Included in this group are the cryopyrin-associated periodic syndromes (CAPS) that are caused by autosomal dominant mutations in the cold-induced autoinflammatory syndrome 1 (CIAS1) gene, also called NLRP3 or NALP3 (NACHT domain-, leucine-rich repeat-, and PYD-containing protein 3)." (PMID 23226210, 2012). "NLRP3-associated autoinflammatory disease (NLRP3-AID) is a spectrum of autosomal dominant inherited inflammasome diseases caused by gain-of-function mutations in the NLRP3 gene encoding cryopyrin and is previously known as cryopyrin-associated periodic syndromes (CAPS)." (PMID 38481988, 2024). "Cryopyrin-associated periodic syndrome (CAPS) represents a group of autosomal dominant autoinflammatory diseases due to gain-of-function mutations in the nucleotide-binding oligomerization domain-like receptors (NLR), family pyrin domain containing 3 (NLRP3) genes." (PMID 37189714, 2023). "Although, to date, no reports have investigated the expression of the NLRP3 inflammasome in brain mast cells, peripheral tissue mast cells from cryopyrin-associated periodic syndrome (CAPS) patients were, for the first time, shown to express functional inflammasomes and secrete IL-1β." (PMID 33499208, 2021). "Cryopyrin-associated periodic syndromes (CAPS), which include familial cold autoinflammatory syndrome (FCAS), Muckle–Wells syndrome (MWS), and neonatal-onset multisystem inflammatory disease (NOMID) are caused by autosomal dominant mutations in the NACHT domain of NLRP3." (PMID 31520179, 2019). "Indeed, migraine without aura attacks are seen in patients with cryopyrin-associated periodic syndromes (CAPS), where IL-1β is overproduced due to mutations in the NLRP3 inflammasome." (PMID 39080518, 2024). "A recent study showed that the molecular target of diarylsulfonylurea inhibitors is an NACHT domain of NLRP3, and as a consequence, MCC950 fails to efficiently inhibit the cryopyrin-associated periodic syndrome (CAPS) forms of NLRP3." (PMID 33673188, 2021). "Gain-of-function mutants of NLRP3, which are the cause of the auto-inflammatory disorder cryopyrin-associated periodic syndrome (CAPS), cannot interact with CARD8, suggesting that the lack of NLRP3 inhibition by CARD8 is the reason for the inflammatory phenotype in CAPS patients." (PMID 38920661, 2024).
Insulin resistance (314 papers, 2012 to 2026). Increased resistance towards insulin, that is, diminished effectiveness of insulin in reducing blood glucose levels. "BHB has additionally been shown to attenuate activation of the NLRP3 inflammasome, which is implicated in metabolic inflammation and insulin resistance." (PMID 41305632, 2025). "NLRP3 drives the maturation and release of IL-1β and IL-18, cytokines implicated in insulin resistance and metabolic derangement." (PMID 40558557, 2025). "Given this association, therapeutic targeting of the NLRP3 inflammasome presents a promising strategy for managing cerebrovascular ischemic disease in the context of insulin resistance." (PMID 40648980, 2025). "Tretinoin has been shown to improve hyperglycemia, insulin deficiency, impaired glucose tolerance, and insulin resistance in gestational diabetes by decreasing NLRP3 inflammasome and pro-inflammatory factors." (PMID 40433411, 2025). "Thioredoxin-interacting protein (TXNIP), a protein associated with insulin resistance, also plays a role in NLRP3 inflammasome activation." (PMID 40433411, 2025). "In the hyperglycemic state of diabetes, elevated ER stress leads to an increase in NLRP3 inflammasome-dependent IL-1β secretion, which causes β-cell dysfunction and promotes obesity and insulin resistance." (PMID 41208954, 2025). "This acetylation is required for the activation of the NLRP3 inflammasome and is linked to aging-related inflammation and insulin resistance." (PMID 40307577, 2025). "Regarding NLRs, sirtuin 2 (SIRT2) deacetylates NLRP3, preventing age-related inflammation and insulin resistance, which can be reversed by NLRP3 K21/22/24R mutations." (PMID 38970666, 2024). "A recent study showed that suppression of NAD‐dependent deacetylase Sirtuin‐2 mediated acetylation of NLRP3 and promoted NLRP3 inflammasome activation, thus contributing to ageing‐associated inflammation and insulin resistance." (PMID 38488468, 2024). "When NLRP3 inflammasomes are overactivated, immune cells secrete excessive inflammatory factors (e.g., IL‐1β), all of which are closely associated with insulin resistance, metabolic syndrome, and diabetic progression." (PMID 38752512, 2024). "P2X7 receptors activate the NLRP3 inflammasome, and excessive activation of the NLRP3 inflammasome causes IL‐1β release, which in turn induces depressive‐like behaviors and insulin resistance in rats." (PMID 38752512, 2024). "For example, SIRT2 deacetylates NLRP3 in macrophages and inactivates the NLRP3 inflammasome, which functions to reverse aging-associated inflammation and insulin resistance." (PMID 39372420, 2024). "NLRP3 activation is associated with metabolic distress, inflammation, and the development of insulin resistance." (PMID 39590865, 2024). "Lifestyle modification aided in weight loss in obese, T2DM patients and decreased the NLRP3 and IL-1β expression and thus, in turn, the insulin resistance." (PMID 37762140, 2023). "More specifically, we highlight the role of the NLRP3 inflammasome in the progression of insulin resistance and miRNA regulation of targets associated with insulin resistance/sensitivity." (PMID 37047241, 2023). "Our study suggests that exercise training is an effective strategy to alleviate insulin resistance and liver injury in elderly pre-diabetic subjects which is probably associated with the inhibition of NLRP3 inflammasome activity." (PMID 36817440, 2023). "SIRT2 and NLRP3 deacetylation prevent and can be targeted to reverse, aging‐associated inflammation, and insulin resistance." (PMID 37143582, 2023). "And the secretion of IL-1β and IL-18, caused by activation of the NLRP3 inflammasome, is emerging as a powerful determinant of metabolic inflammation and insulin resistance in T2DM patients." (PMID 35355717, 2022).
Insulin resistance (continued). "Statins impair insulin signaling causing statin-induced insulin resistance in adipose tissue, coincident with activation of NLR family pyrin domain-containing 3 (NLRP3) inflammasome and impaired insulin-stimulated lipogenesis in adipocytes." (PMID 36558473, 2022). "Together, these findings suggest that AS3MT-promoted and METTL14-dependent RNA m6A modification plays a critical role in arsenic-exposure-caused NLRP3 inflammasome activation and subsequent hepatic insulin resistance." (PMID 36233132, 2022). "In line with this concept, mice genetically deficient in NLRP3 are protected against HFD–induced insulin resistance." (PMID 33806797, 2021). "In this context, SIRT2 overexpression in old macrophages reduced NLRP3 acetylation and activation, reversing aging-associated insulin resistance and neuroinflammation." (PMID 33803627, 2021). "Improvement in insulin signaling was also evident in the skeletal muscle of NLRP3-deficient mice, while the knockdown of NLRP3 expression partially reversed perilipin 2-induced insulin resistance in C2C12 myoblast via upregulation of IRS-1 mRNA." (PMID 32545355, 2020). "Thioredoxin (TRX)-interacting protein (TXNIP), a protein linked to NLRP3 inflammasome activation, is responsible for insulin resistance and is targeted too by novel therapeutic molecules in clinical trials." (PMID 33172097, 2020). "Our preceding data demonstrate that Kir6.1 ablation causes activation of the NLRP3 inflammasome and insulin resistance, which can be overcome by transient expression of Kir6.1." (PMID 31387986, 2019). "It has been demonstrated that excessive activation of the NLRP3 inflammasome impairs glucose metabolism and enhances insulin resistance, which is associated with the onset and progression of metabolic diseases such as T2D48." (PMID 31387986, 2019). "The TXNIP interaction is a specific feature of NLRP3, binding protein to the NLRP3 inflammasome, and is associated with insulin resistance and multiple organ damage." (PMID 31174550, 2019). "NACHT, LRR, and PYD domains-containing protein 3 (NLRP3) inflammasome activation by lipid is a cause of metabolic inflammation and insulin resistance in obesity." (PMID 29650965, 2018). "The NLRP3 inflammasome activity promotes insulin resistance and genetic deficiency in NLRP3 inflammasome, ASC or caspase-1 ameliorates insulin signaling pathway in obese mice." (PMID 28765650, 2017). "The NLRP3 inflammasome and the release of inflammatory cytokines have been indicated to cause insulin resistance, and anti-inflammation therapeutic strategy is becoming promising in the treatment of T2D." (PMID 29096724, 2017). "A hallmark of insulin resistance is the deposition of amyloid in the islets and this has been linked to the activation of NLRP3 inflammasome in local macrophages, triggering IL-1β processing and release." (PMID 26257839, 2015). "Another common SNP associated with mRNA stability, NLRP3 rs10754558, was linked to insulin resistance and increased risk for T2D in Chinese Han population." (PMID 26273672, 2015). "In contrast to type 1 diabetes(T1DM), DR associated with T2DM is marked by insulin resistance and persistent low-grade inflammation, which may intensify the abnormal activation of the NLRP3 inflammasome." (PMID 40987781, 2025). "The NLRP3/IL-1β pathway is also implicated in inducing insulin-resistance." (PMID 39899119, 2025). "Notably, both insulin resistance, autophagy activation and NLRP3-meidated inflammation were critical risk factor of PCOS." (PMID 38302986, 2024). "NLRP3 activation has been described in response to hyperglycemia, saturated fatty acids, and islet amyloid polypeptide and is linked to glucose intolerance, insulin resistance, and beta-cell death." (PMID 37400850, 2023). "Notably, the NLRP3 inflammasome, in particular, has been implicated in β-cell pyroptosis and insulin resistance." (PMID 37859981, 2023).